HAUS4 (HAUS augmin like complex subunit 4)
Description:
Contributes to mitotic spindle assembly, maintenance of centrosome integrity and completion of cytokinesis as part of the HAUS augmin-like complex.
Synonyms: C14orf94; FLJ20424
Tractability: PROTAC: ubiquitination databases record sites on it.
Gene: Protein-coding gene on chromosome 14 (22,946,228 to 22,957,161, reverse strand). Ensembl gene ENSG00000092036.
Subcellular location: Cytoplasm, cytoskeleton, microtubule organizing center, centrosome; Cytoplasm, cytoskeleton, spindle
Pathways (Reactome):
Cell Cycle: AURKA Activation by TPX2; Loss of Nlp from mitotic centrosomes; Loss of proteins required for interphase microtubule organization from the centrosome; Recruitment of NuMA to mitotic centrosomes; Recruitment of mitotic centrosome proteins and complexes; Regulation of PLK1 Activity at G2/M Transition
Organelle biogenesis and maintenance: Anchoring of the basal body to the plasma membrane
Gene Ontology:
Molecular function: protein binding
Biological process: centrosome cycle; spindle assembly; regulation of microtubule nucleation
Cellular component: centrosome; HAUS complex; mitotic spindle microtubule; cytosol; spindle
Genetic constraint (gnomAD): Loss-of-function variants: 26 observed, 40.52 expected, observed/expected ratio (o/e) 0.64, 90% interval 0.47 to 0.89. The upper end of that interval is the gene's LOEUF score, 0.89, which puts it in group 3 of 6, group 1 being the genes least tolerant of losing a copy. Missense variants: 292 observed, 357.67 expected, observed/expected ratio (o/e) 0.82, 90% interval 0.74 to 0.9. Synonymous variants: 119 observed, 141.27 expected, observed/expected ratio (o/e) 0.84, 90% interval 0.73 to 0.98.
Homologues: Orthologues: chimpanzee HAUS4 (99% identical), macaque HAUS4 (96% identical), rabbit HAUS4 (88% identical), pig HAUS4 (86% identical), rat Haus4 (81% identical), guinea pig HAUS4 (81% identical), mouse Haus4 (78% identical), tropical clawed frog haus4 (43% identical), zebrafish haus4 (34% identical).
Diseases named in the same sentence as HAUS4 in open-access papers:
HAUS4 is named in the same sentence as 3 diseases in open-access papers, as found by Europe PMC text mining. Sharing a sentence is not in itself a finding about the gene and the disease. The quoted sentences say what the papers report.
glioma (1 paper, 2023). A benign or malignant brain and spinal cord tumor that arises from glial cells (astrocytes, oligodendrocytes, ependymal cells). "Low expression of HAUS4 and HAUS6 and high expression of HAUS1, HAUS3, HAUS5, HAUS7, HAUS8 may be risk factors for poor prognosis in glioma patients." (PMID 37161065, 2023). "The research found that expression levels of the Augmin family genes HAUS1, HAUS3, HAUS4, HAUS5, HAUS6, HAUS7, and HAUS8 was all related with survival rates of glioma patients." (PMID 37161065, 2023).
tumor (2 papers, 2023). "The reduced clonogenic growth of MDA-MB-231 herein may be attributed to the upregulation of some tumor suppressor proteins such as TSPAN6, MAPK6, SPRY2, HAUS4, stomatin (STOM) and conserved oligomeric golgi complex subunit 8 (COG8)." (PMID 38283944, 2023).
HAUS4 also shares sentences with these, for which no sentence is quoted: prostate carcinoma (1 paper).